CCDC50 (coiled-coil domain containing 50)
Description:
Involved in EGFR signaling.
Synonyms: C3orf6; Ymer; DFNA44
Tractability: PROTAC: ubiquitination databases record sites on it; its protein half-life has been measured.
Gene: Protein-coding gene on chromosome 3 (191,329,085 to 191,398,659, forward strand). Ensembl gene ENSG00000152492.
Subcellular location: Cytoplasm
Subcellular location (Human Protein Atlas): Cytosol; Basal body
Gene Ontology:
Molecular function: protein binding; ubiquitin protein ligase binding
Biological process: sensory perception of sound
Cellular component: cytosol; cytoplasm
Genetic constraint (gnomAD): Loss-of-function variants: 43 observed, 59.45 expected, observed/expected ratio (o/e) 0.72, 90% interval 0.57 to 0.93. The upper end of that interval is the gene's LOEUF score, 0.93, which puts it in group 3 of 6, group 1 being the genes least tolerant of losing a copy. Missense variants: 518 observed, 552.8 expected, observed/expected ratio (o/e) 0.94, 90% interval 0.87 to 1.01. Synonymous variants: 211 observed, 196.77 expected, observed/expected ratio (o/e) 1.07, 90% interval 0.96 to 1.2.
Gene-disease validity (ClinGen):
ClinGen rates the evidence that CCDC50 causes each of these diseases.
nonsyndromic genetic hearing loss (autosomal dominant): Limited. A disease characterized by hearing loss that is not part of a larger syndrome.
Homologues: Orthologues: chimpanzee CCDC50 (99% identical), macaque CCDC50 (92% identical), rabbit CCDC50 (83% identical), pig CCDC50 (83% identical), dog CCDC50 (81% identical), guinea pig CCDC50 (77% identical), mouse Ccdc50 (76% identical), rat Ccdc50 (74% identical), tropical clawed frog ccdc50 (43% identical), zebrafish ccdc50a (33% identical), Drosophila melanogaster CG10283 (20% identical), Caenorhabditis elegans R10H1.1 (9% identical).
Diseases named in the same sentence as CCDC50 in open-access papers:
CCDC50 is named in the same sentence as 38 diseases in open-access papers, as found by Europe PMC text mining. Sharing a sentence is not in itself a finding about the gene and the disease. The quoted sentences say what the papers report.
hearing loss (5 papers, 2014 to 2024). "Here, we report a previously unreported frameshift mutation in CCDC50 [c.828_858del, p.(Asp276Glufs*40)] causing non-syndromic hearing impairment in a second Spanish family." (PMID 37165931, 2023). "CCDC50 with a duplication in exon 11 was reported to be associated with progressive hearing loss in the Spanish group, but to our knowledge, no reports were found to be related to CCDC50 with neurodevelopmental disorders." (PMID 32477112, 2020). "In epithelial patterning (CD−M5), Tmtc2, Hgf, and Ccdc50 were associated with NSHL and Ror1 with hearing loss and auditory neuropathy." (PMID 39684410, 2024). "Likewise, the CCDC50 protein is expressed during inner ear maturation and in the mature cochlea, the latter correlating with the patients' postlingual appearance of the hearing impairment." (PMID 37165931, 2023).
mantle cell lymphoma (4 papers, 2015 to 2025). Mantle cell lymphoma is a rare form of malignant non-Hodgkin lymphoma affecting B lymphocytes in the lymph nodes in a region called the ``mantle zone''. "It has been reported CCDC50 is involved in the progression of renal clear cell carcinoma and mantle cell lymphoma." (PMID 37552104, 2023). "CCDC50 is ubiquitously expressed across various tissues, and previous studies have demonstrated its role in promoting cell survival and NF-κB inducibility in mantle cell lymphoma and chronic lymphocytic leukemia." (PMID 40526100, 2025). "In Hepatocellular Carcinoma (HCC), Mantle Cell Lymphoma (MCL) and Chronic Lymphocytic Leukemia (CLL), CCDC50 is required for cell survival." (PMID 37684379, 2023).
viral infection (4 papers, 2023 to 2026). "Although there is limited specific information on the expression changes of CCDC91 in response to viral infections, CCDC50, a related gene to CCDC91, negatively regulated the type I IFN signaling pathway initiated by RIG-I-like receptors (RLRs), the sensors for RNA viruses." (PMID 39066192, 2024). "To investigate whether MDA5 interacts with p62, Tollip, and CCDC50 during viral infection, we conducted Co-IP analyses before and post-EMCV infection." (PMID 39285245, 2024).
deafness (3 papers, 2015 to 2023). An inherited or acquired condition characterized by the complete loss of the ability to hear from one or both ears. "Sequencing of 71 known deafness genes using our custom-designed next-generation sequencing (NGS) panel (OTO-NGS-panel V1) on DNA from individual II:3 identified a 31 bp deletion in heterozygosis in CCDC50 (c.828_858del)." (PMID 37165931, 2023). "In the future, this approach may be used to test the feasibility of treating other inherited deafness cases in which the SV is the predominant site affected (e.g. mutations in KCNE1, CCDC50, DFNA5, MYH14, TFCP2L3, TMPRSS3 genes)." (PMID 26084842, 2015).
hepatocellular carcinoma (3 papers, 2023 to 2024). A malignant tumor that arises from hepatocytes. "Additionally, CCDC50 promotes tumor cell proliferation by inhibiting c-Myc ubiquitin-mediated degradation and also contributes to the development of hepatocellular carcinoma through the Ras/Foxo4 signaling pathway." (PMID 38515748, 2024). "Due to the heterogeneity of tumor cells and immune cells, the expression of CCDC50 in hepatocellular carcinoma may be significantly different from the correlation between different immune cells." (PMID 37552104, 2023). "Further, CCDC50 could regulate Ras signalling pathway and promote mice hepatocellular carcinoma." (PMID 37552104, 2023). "Therefore, it is crucial to reveal whether CCDC50 is regulated by DNA methylation and then abnormally expressed in hepatocellular carcinoma." (PMID 37552104, 2023).
autosomal dominant deafness (2 papers, 2021 to 2023). "Among the genes involved in non-syndromic autosomal dominant SNHL is CCDC50 (MIM 611051), which maps to chromosome 3q28-29 within the critical interval of the autosomal dominant deafness locus DFNA44." (PMID 37165931, 2023).
gastric cancer (2 papers, 2022 to 2023). A primary or metastatic malignant neoplasm involving the stomach. "In addition to LRRFIP2, CCDC50, another splicing candidate of ESRP1, also showed skipping exon event and BICD2 showed retained intron event occurring in gastric cancer cells depending on the expression of ESRP1." (PMID 36307405, 2022).
melanoma (2 papers, 2024 to 2025). A malignant, usually aggressive tumor composed of atypical, neoplastic melanocytes. "Silencing CCDC50 significantly suppresses melanoma cell proliferation, invasion, and metastasis, while improving survival in mouse models, underscoring its tumor-promoting function and potential as a therapeutic target." (PMID 41516242, 2025). "High CCDC50 expression correlates with increased malignancy, metastasis, and poor overall survival in melanoma patients." (PMID 41516242, 2025). "In melanoma CCDC50 is upregulated and the galectin-3/CCDC50-mediated lysophagy mechanism supports tumour growth and, potentially, also works in other tumours." (PMID 38990375, 2024).
Obesity (2 papers, 2017 to 2024). Accumulation of substantial excess body fat. "Other hub genes, including CCDC50, ORMDL3, PCCA and NAALAD2, have diverse cellular functions and have not been previously implicated as obesity candidate genes." (PMID 28496128, 2017).
renal clear cell carcinoma (2 papers, 2022 to 2023). "CCDC50-S promotes the metastasis of renal clear cell carcinoma, but CCDC50-FL and sh-CCDC50 inhibit the metastasis of renal clear cell carcinoma." (PMID 36147484, 2022).
epilepsy (1 paper, 2020). A brain disorder characterized by episodes of abnormally increased neuronal discharge resulting in transient episodes of sensory or motor neurological dysfunction, or psychic dysfunction. "While most of genes are known to be related to ASD, ID or epilepsy, ABCC2, CCDC50 and SLC26A4 were not reported to be related to neurodevelopmental disorder according to OMIM." (PMID 32477112, 2020).
inflammatory bowel disease (1 paper, 2025). A spectrum of small and large bowel inflammatory diseases of unknown etiology. "For 6 of these genes, a role in inflammatory bowel disease is supported by other criteria: GWAS associations with nearby SNPs (ANKRD55, LPP, PDLIM7), experimental perturbation (CCDC50, VCAM1), association with measured protein levels (IL6, VCAM1), or drug effects (IL6, VCAM1)." (PMID 40996888, 2025).
leukemia (1 paper, 2025). A malignant (clonal) hematologic disorder, involving hematopoietic stem cells and characterized by the presence of primitive or atypical myeloid or lymphoid cells in the bone marrow and the blood. "Four of these genes were reported for leukemias (IRS1, RUNX2, CCDC50 and ROBO3) and four others were reported to be involved in other types of cancers (NSG1, CAMK1D, CD3E, KLF8)." (PMID 41146244, 2025).
liver cancer (1 paper, 2023). An epithelial or non-epithelial malignant neoplasm that arises from the liver. "Furthermore, we found that the level of DNA methylation of CCDC50 was downregulated in liver cancer tissue and was negatively correlated with liver cancer metastasis." (PMID 37552104, 2023).
lung adenocarcinoma (1 paper, 2023). A carcinoma that arises from the lung and is characterized by the presence of malignant glandular epithelial cells. "CCDC50 is known to mediate apoptosis via the NF-κB pathway and had prognostic predictive value in lung adenocarcinoma." (PMID 38111587, 2023).
lung carcinoma (1 paper, 2022). "The biological functions of newly discovered HLA-DRB5 and CCDC50 risk genes in lung cancer were further explored." (PMID 36147484, 2022).
myeloid neoplasm (1 paper, 2025). Proliferation of myeloid cells originating from a primitive stem cell. "Our findings demonstrate that the mutational landscape of BPDCN is similar to that observed in other myeloid neoplasms, and we identified CCDC50 as a potential biomarker for this disease." (PMID 40526100, 2025).
osteoporosis (1 paper, 2020). A condition of reduced bone mass, with decreased cortical thickness and a decrease in the number and size of the trabeculae of cancellous bone (but normal chemical composition), resulting in increased fracture incidence. "Our study indicates that myostatin is a promising candidate target for inhibiting RANKL-mediated osteoclastogenesis and might participate in therapy for osteoporosis, and that the Ccdc50 gene plays a significant role in the regulatory process." (PMID 33536903, 2020).
tumor (9 papers, 2011 to 2025). "The qRT‒PCR results revealed that the levels of HLA-DRB5 were lower and the levels of CCDC50 were higher in five high-risk tumor tissues." (PMID 36147484, 2022). "The protein levels of HLA-DRB5 were lower and the levels of CCDC50 were higher in high-risk tumor tissues." (PMID 36147484, 2022). "CCDC50 recognizes and promotes the autophagic clearance of damaged lysosomes, maintaining redox balance and supporting tumor cell survival." (PMID 41516242, 2025). "However, another study showed that CCDC50 maintains long-term activation of NF-κB signaling in Fas-stimulated thymocytes, and CCDC50 is required for tumor survival and activates NF-κB signaling in CLL and MCL." (PMID 37684379, 2023). "We further validated the expression of CCDC50 and CR2 at the protein level using IHC, which confirmed their significant overexpression in tumor tissues." (PMID 38515748, 2024). "Our results demonstrated that CCDC50 not only showed significantly positive correlations with ABC subtype, tumor stage and number of extranodal sites, but also suggested poor outcomes in DLBCL patients." (PMID 37684379, 2023). "High CCDC50 expression had worse OS in diverse subgroups of HCC, including residual tumour, gender, age, race, histologic grade, weight, TNM stage, and tumour status." (PMID 37552104, 2023). "We observed significant correlations between CCDC50 expression and DLBCL subtype, tumor stage and number of extranodal sites (p < 0.05, n = 414)." (PMID 37684379, 2023). "Subsequently, in exploring the biological mechanism of CCDC50 in ABC-DLBCL, we present multiple evidence supporting that CCDC50 could stabilize c-Myc to promote tumor proliferation." (PMID 37684379, 2023). "One DEE (ENSE00001334610) of CCDC50 in pattern 2 was significantly down-regulated in tumor tissue (P<0.001), while another DEE (ENSE00001552245) exhibited no significant expression difference between tumor and non-tumor tissues (P = 0.9496)." (PMID 22043308, 2011).
cancer (4 papers, 2020 to 2025). A tumor composed of atypical neoplastic, often pleomorphic cells that invade other tissues. "TIMER database was used to reveal the relationship between the infiltration levels and CCDC50 expression in 32 types of cancers." (PMID 38301044, 2024). "Firstly, we combined the TCGA and GTEx databases, and confirmed that the expression of CCDC50 was significantly lower in 14 cancer tissues than normal tissues." (PMID 37552104, 2023). "To determine the protein levels of CCDC50 in different types of cancer, we analysed the UALCAN database and found that the protein expression of CCDC50 was low in 4 types of cancer, whereas it was high in 5 types of cancer including HCC." (PMID 37552104, 2023). "For example, in TPRG1 associated with HNSCC potential oncogene TP63, LPP played the role of cancer cell migration, and CCDC50 was essential for cancer cell survival." (PMID 32455963, 2020). "In addition, CCDC50 was up-regulated in 12 types of cancer including HCC." (PMID 37552104, 2023).
infection (1 paper, 2026). The state of being infected such as from the introduction of a foreign agent such as serum, vaccine, antigenic substance or organism. "During porcine deltacoronavirus (PDCoV) infection, NSP5 cleaves CCDC50 at glutamine 171 (Q171), a conserved site also processed by NSP5 from PEDV, TGEV, and SARS-CoV-2." (PMID 41817175, 2026).
neurological disorders (1 paper, 2020). "Overall, the present study demonstrates a novel mechanism of CCDC50 function in neuronal development and provides new insight into the link between CCDC50 function and the aetiology of neurological disorders." (PMID 33277610, 2020).
CCDC50 also shares sentences with these, for which no sentence is quoted: Chronic Lymphocytic Leukemia (2 papers); acute myeloid leukemia (1); auditory neuropathy (1); autism spectrum disorder (1); breast tumor (1); diabetes (1); diffuse large B-cell lymphoma (1); glaucoma (1); Hearing impairment (1); Intellectual disability (1); metastatic disease (1); neurodevelopmental disorder (1); osteoarthritis (1); psoriatic arthritis (1); sensorineural hearing loss (1); uveal melanoma (1).